MTDH (metadherin)
Description:
Down-regulates SLC1A2/EAAT2 promoter activity when expressed ectopically. Activates the nuclear factor kappa-B (NF-kappa-B) transcription factor. Promotes anchorage-independent growth of immortalized melanocytes and astrocytes which is a key component in tumor cell expansion. Promotes lung metastasis and also has an effect on bone and brain metastasis, possibly by enhancing the seeding of tumor cells to the target organ endothelium. Induces chemoresistance.
Synonyms: AEG-1; AEG1; LYRIC; 3D3; LYRIC/3D3
Tractability: Antibody: UniProt predicts a signal peptide or a membrane-spanning region. PROTAC: ubiquitination databases record sites on it; its protein half-life has been measured.
Gene: Protein-coding gene on chromosome 8 (97,644,013 to 97,730,260, forward strand). Ensembl gene ENSG00000147649.
Subcellular location: Endoplasmic reticulum membrane; Nucleus membrane; Cell junction, tight junction; Nucleus, nucleolus; Cytoplasm, perinuclear region
Subcellular location (Human Protein Atlas): Endoplasmic reticulum
Gene Ontology:
Molecular function: double-stranded RNA binding; NF-kappaB binding; protein binding; RNA binding; RNA polymerase II-specific DNA-binding transcription factor binding; transcription coactivator activity; transcription coregulator activity
Biological process: lipopolysaccharide-mediated signaling pathway; mRNA catabolic process; negative regulation of apoptotic process; negative regulation of transcription by RNA polymerase II; positive regulation of angiogenesis; positive regulation of autophagy; positive regulation of canonical NF-kappaB signal transduction; positive regulation of phosphatidylinositol 3-kinase/protein kinase B signal transduction; regulation of transcription by RNA polymerase II; positive regulation of DNA-templated transcription
Cellular component: cytoplasm; endoplasmic reticulum; nuclear body; nucleus; perinuclear region of cytoplasm; apical plasma membrane; bicellular tight junction; endoplasmic reticulum membrane; intercellular canaliculus; nuclear membrane; nucleolus
Genetic constraint (gnomAD): Loss-of-function variants: 15 observed, 43.16 expected, observed/expected ratio (o/e) 0.35, 90% interval 0.23 to 0.54. The upper end of that interval is the gene's LOEUF score, 0.54, which puts it in group 2 of 6, group 1 being the genes least tolerant of losing a copy. Missense variants: 529 observed, 548.17 expected, observed/expected ratio (o/e) 0.97, 90% interval 0.9 to 1.04. Synonymous variants: 231 observed, 216.78 expected, observed/expected ratio (o/e) 1.07, 90% interval 0.96 to 1.19.
Homologues: Orthologues: chimpanzee MTDH (99% identical), macaque MTDH (99% identical), mouse Mtdh (91% identical), rat Mtdh (90% identical), guinea pig MTDH (90% identical), tropical clawed frog mtdh (50% identical), zebrafish mtdha (34% identical), zebrafish mtdhb (31% identical). Paralogues in human: MAMSTR (12% identical).
Diseases named in the same sentence as MTDH in open-access papers:
MTDH is named in the same sentence as 183 diseases in open-access papers, as found by Europe PMC text mining. Sharing a sentence is not in itself a finding about the gene and the disease. The quoted sentences say what the papers report.
breast carcinoma (148 papers, 2009 to 2026). "Taken together, these findings suggest that the loss of MTDH S-palmitoylation enhances the migration ability in breast cancer cells." (PMID 41318030, 2025). "The upregulation of MTDH is associated with a better prognosis of Her2-positive breast cancer patients." (PMID 38977630, 2024). "Despite numerous studies exist regarding the function of MTDH in breast cancer, the association between MTDH polymorphisms and breast cancer risk remains unreported." (PMID 38977630, 2024). "In breast cancer, the overexpression of MTDH is closely associated with carcinogenesis, development, metastasis, and chemoresistance." (PMID 35046810, 2021). "Metadherin (MTDH; also called AEG1, LYRIC) as a pro-metastasis gene that resides in 8q22, a frequently amplified genomic locus linked to poor relapse-free survival of breast cancer." (PMID 32083506, 2020). "The elevated MTDH expression was associated with poor overall survival rates in breast cancer patients, based on the cBioPortal and GEPIA 2 data analyses." (PMID 32074085, 2020). "The increased expression of MTDH in breast cancer tissues was validated by gene mutation analysis using the cBioPortal data." (PMID 32074085, 2020). "Escalating evidence demonstrates that metadherin (MTDH) is associated with a number of cancer signaling pathways as well as breast cancer therapy resistance, making it an attractive therapeutic target." (PMID 31979093, 2020). "MTDH is a type-two transmembrane protein containing an extracellular lung homing domain which is implicated in breast cancer metastasis to the lung." (PMID 31131259, 2019). "Expression of MTDH is implicated in breast cancer stem cell (CSC) growth and tumor resistance to paclitaxel and trastuzumab." (PMID 31131259, 2019). "Amplification of 8q22, including the MTDH locus is associated with chemoresistance and metastasis in aggressive breast cancer." (PMID 31131259, 2019). "Ward A13et al. showed that high MTDH expression was remarkably associated with short DFS in breast cancer (P = 0.0233) with a cohort of patients from public data (GSE1378)." (PMID 27917902, 2016). "Breast cancer cells adhesion and proliferation increase with decreasing HA particle size and concentration; MSCs upregulate the expression of the well-known metastasis-associated gene metadherin within breast cancer cells." (PMID 27027241, 2016). "Specifically, the results our meta-analysis indicates that high MTDH expression is strongly associated with high risk of tumor metastasis and worse prognosis in breast cancer." (PMID 27917902, 2016). "Decreased miR-320a expression was associated with high MTDH expression which contributed to breast cancer metastasis and poor prognosis." (PMID 27229534, 2016). "Down-regulation of MTDH expression can reduce the proliferation of breast cancer cells and increase their susceptibility to doxorubicin." (PMID 25993398, 2015). "The susceptibility of breast cancer cells to several chemotherapy drugs reveals a significant increase after MTDH silencing." (PMID 25993398, 2015). "Subgroup analyses proves that MTDH is implicated in trastuzumab resistance in HER2 positive breast cancer, which is further confirmed by elevated MTDH but reduced PTEN expressions in trastuzumab-resistant breast cancer cells." (PMID 25417825, 2014). "MTDH was reported to be overexpressed in breast cancer and to be associated with poor prognosis, due to its participation in tumorigenesis, metastasis and chemoresistance." (PMID 25333261, 2014). "Our group was the first to discover a significant association between MTDH and tumor susceptibility: that is, that 2 MTDH variants are associated with breast cancer." (PMID 23240043, 2012). "Our group has also previously found that variants in MTDH are significantly associated with breast cancer." (PMID 23240043, 2012). "It has been reported that overexpression of MTDH is associated with progression of disease and poorer prognosis in breast cancer." (PMID 21408129, 2011).
breast carcinoma (continued). "Metadherin (MTDH) has been reported to be associated with cancer progression in various types of human cancers including breast cancer." (PMID 20565850, 2010). "Overexpression of MTDH is associated with doxorubicin sensitivity of breast cancer." (PMID 38977630, 2024). "Furthermore, the expression of MTDH is prognostically linked to diverse molecular subtypes among patients with breast cancer following therapeutic intervention." (PMID 38977630, 2024). "To verify whether MTDH and IL-10 protein expressions were linked with clinicopathological parameters of breast cancer, we enrolled 265 breast cancer patients and performed immunohistochemistry of MTDH and IL-10." (PMID 33003428, 2020). "Moreover, the MTDH gene is frequently amplified in breast cancer, and the increased MTDH expression is associated with increased aggressiveness, paclitaxel resistance, and trastuzumab resistance in breast cancer patients." (PMID 32074085, 2020). "Elevated expressions of MTDH are associated with poor prognoses in breast cancer and TNBC patients." (PMID 31979093, 2020). "In addition, the co-culture of MSCs and MDA-MB-231 in this bone model revealed that MSCs have the capacity to upregulate the expression of the well-known metastasis-associated gene metadherin within breast cancer cells." (PMID 27027241, 2016). "Our results showed that MTDH, as a cell surface protein, is significantly associated with the mortality of patients with reproduction malignancies (HR = 3.647), including breast cancer (HR = 2.728), ovarian cancer (HR = 4.525), cervical cancer (HR = 2.524) and endometrial cancer (HR = 2.524)." (PMID 27917902, 2016). "Similarly, the susceptibility of breast cancer cells to multiple chemotherapeutic drugs exhibits a significant enhancement due to the silencing of MTDH gene." (PMID 25993398, 2015). "The most obvious inhibition (61.69%) was observed in MDA-MB-231 cell line, but the least inhibition (15.51%) was observed in MCF7/ADR cell line, indicating that the expression level of MTDH is negatively associated with the susceptibility of breast cancer cells to doxorubicin." (PMID 25993398, 2015). "Therefore, in order to clarify the relationship between MTDH gene and chemotherapeutic susceptibility of breast cancer, we have conducted this study at the cellular level." (PMID 25993398, 2015). "Similarly, previous investigation has shown that suppressing MTDH can increase the susceptibility of breast cancer cells to chemotherapeutic drugs and stressors." (PMID 25993398, 2015). "MTDH gene plays a promoting role in the proliferation of breast cancer cells and its high expression may be associated with doxorubicin sensitivity of breast cancer." (PMID 25993398, 2015). "Variants in MTDH have been associated with susceptibility to breast cancer." (PMID 23240043, 2012). "MTDH is involved in several signaling pathways and amplification of MTDH promotes metastases, enhances chemo-resistance and is associated with poor outcome in female breast cancer patients." (PMID 22527098, 2012). "Thus, we investigated all variants of the MTDH gene and explored the association of the variants with breast cancer development." (PMID 21408129, 2011). "Given the recent interest in the MTDH gene and its suggested important role in the development of breast cancer, this study was conducted to investigate both known and novel SNPs to analyze if any of these variants of MTDH contribute to the risk of breast cancer development." (PMID 21408129, 2011). "While additional study on the MTDH gene is necessary, variants of MTDH may prove to be potential markers for breast cancer development, prognostic indicators for disease progression, and possible foci for future targeted therapy." (PMID 21408129, 2011). "Additionally, the MTDH (1681 G>A, rs2331652) polymorphism was also found to increase susceptibility for breast cancer development." (PMID 21408129, 2011).
breast carcinoma (continued). "Current studies have revealed that MTDH could be a prognostic factor in breast cancer: its high expression is associated with poor survival." (PMID 22195048, 2011). "In addition, elevated expression of MTDH has been associated with breast cancer therapy resistance." (PMID 31979093, 2020). "Taken together, these findings suggest that S-palmitoylation of MTDH plays a critical role in regulating lipid composition in breast cancer cells, particularly affecting levels of TG, PC, and PE." (PMID 41318030, 2025). "Beside a previous study also supports this notion, showing that MTDH enhances the sensitivity of breast cancer cells to ferroptosis." (PMID 41318030, 2025). "For example, breast cancer patients with poor clinical outcome showed gains of chromosome 8q22 that contained the AEG-1/MTDH gene." (PMID 40282551, 2025). "In parallel, in 2004, AEG-1 was cloned as a cell membrane protein facilitating breast cancer metastasis and was termed metadherin and given the GenBank symbol MTDH." (PMID 40282551, 2025). "Mechanistically, the MTDH/NF-κB (p65)/QPCT signaling axis was assessed as a factor promoting breast cancer progression and mediate in DOX sensitivity." (PMID 38417050, 2024). "Through in-depth and meticulous functional experiments, it was demonstrated that MTDH, located in this local amplicon, plays a crucial oncogenic role in breast cancer chemotherapy resistance and distant organ metastasis." (PMID 38862581, 2024). "Lobaplatin inhibits cell proliferation and induces apoptosis by downregulating MTDH in breast cancer." (PMID 38977630, 2024). "Knockdown of lncRNA TP73-AS1 inhibits in vitro breast cancer cell carcinogenesis by targeting miRNA-125a-3p to suppress MTDH levels." (PMID 38977630, 2024). "MiR-30a-5p is a key regulatory molecule in breast tumors, and it inhibited breast cancer cell migration, invasion, and glycolysis by targeting MTDH (3′-untranslated region of metadherin) and LDHA (Lactate dehydrogenase A)." (PMID 39239646, 2024). "The tumor suppressor FBXW7 also hinders breast cancer proliferation and promotes apoptosis by degrading MTDH." (PMID 38977630, 2024). "The OH groups of FDG were then used for conjugation with the anti-metadherin (anti-MTDH) antibody, specific for MTDH, a surface protein overexpressed in breast cancer cells." (PMID 38611815, 2024). "Non-coding RNAs regulate the expression and function of MTDH by affecting their binding to miRNAs in breast cancer." (PMID 38977630, 2024). "Taken together, these findings indicate the necessity for further exploration of Metadherin in breast cancer and its potential as a biomarker for prognosticating the outcomes of breast cancer patients." (PMID 38253625, 2024). "In breast cancer cell lines, the metadherin (MTDH) gene improved cell viability and angiogenesis in endothelial cells." (PMID 38392967, 2024). "Further, to investigate the correlation between QPCT and MTDH expression and its effect on prognosis, we included 56 patients with locally advanced breast cancer in this study." (PMID 38417050, 2024). "For instance, circHIPK3 in breast cancer-derived exosomes promotes angiogenesis in the tumor microenvironment through elevating the expression of MTDH by sponging miR-124-3p." (PMID 38977630, 2024). "The present study also demonstrates that QPCT, which is regulated by the MTDH/NF-κB (p65) axis, promotes the proliferation, invasion, and migration of breast cancer cells and affected their DOX sensitivity." (PMID 38417050, 2024). "Elevated MTDH expression predicts a better prognosis for HER-2 positive breast cancer patients following combined therapy of neoadjuvant chemotherapy and trastuzumab." (PMID 38977630, 2024). "Subsequently, the role of high expressions levels of QPCT and MTDH in promoting breast cancer progression and poor prognosis was validated both in breast cancer patients and through in vitro experiments." (PMID 38417050, 2024).
breast carcinoma (continued). "A close relationship has been observed between MTDH expression and the poor prognosis of breast cancer patients." (PMID 38977630, 2024). "The results further confirmed that CXCL13 and MTDH can be used as independent prognostic factors of breast cancer to predict the survival of breast cancer patients." (PMID 38795164, 2024). "Tumor cells have been shown to express Metadherin at high levels and to be closely related to cell proliferation, apoptosis, and migration in breast cancer, nasopharyngeal carcinoma, colorectal cancer and ovarian cancer." (PMID 38253625, 2024). "Studies in breast cancer models revealed that the primary function of MTDH in cancer involves interaction with SND1 and protection from degradation." (PMID 37973913, 2023). "Breast cancer (BRCA)-derived exosomal homeodomain-interacting protein kinase 3 circRNA (circHIPK3) enhances metadherin (MTDH) expression in endothelial cells by acting as a sponge for miR-124-3p, resulting in angiogenesis in BRCA cells." (PMID 37753074, 2023). "As a mechanism, the authors suggested that the SIRT1-mediated inhibition of the proliferation of the breast cancer cells was due to the downregulation of c-Myc, which resulted in the downregulation of MTDH." (PMID 36291902, 2022). "Metadherin (MTDH) is a newly discovered cancer-associated protein that promotes EMT, invasion and metastasis in various types of cancers, including breast cancer." (PMID 35847022, 2022). "The locked nucleic acid (LNA)-modified ASOs have already been tested to decrease metadherin (MTDH) expression which promotes colorectal, lung, and breast cancer growth and metastasis." (PMID 35189921, 2022). "Recent studies have reported that GABAA receptor-associated protein-like 1 (GABARAPL1) promotes the growth and metastasis of breast cancer cells via metadherin (MTDH)." (PMID 34445736, 2021). "In conclusion, MTDH regulated the biological functions and drug resistance of Gem-treated breast cancer cells and affected tumor growth through targeting miR-9-3p." (PMID 34552061, 2021). "For instance, LINC01638 is firstly found to promote breast cancer progression through activating MTDH-Twist1 signaling." (PMID 33714208, 2021). "In particular, the reduction of MTDH strongly upregulated the expression of RKIP especially in breast cancer cells." (PMID 33802672, 2021). "We observed that MCF7 showed the lowest sensitivity to Gem, while HCC1806 was the most sensitive to Gem, indicating that higher MTDH expression in breast cancer cells was correlated with a lower sensitivity of cells to Gem." (PMID 34552061, 2021). "Downregulation of PTEN was previously related to tamoxifen-resistance in the MCF-7 breast cancer cell line overexpressing the tumor suppressor gene MTDH." (PMID 34359587, 2021). "In 2004, Brown and Ruoslahti found that breast cancer cells with high-expressed MTDH transfer easily to the lungs, but its metastasis into the lungs is greatly reduced by knocking out the MTDH gene through siRNA technology in experimental mice." (PMID 34552061, 2021). "We further investigated the effects of MTDH targeting miR-9-3p on the biological characteristics and apoptotic protein expressions of Gem-treated breast cancer cells." (PMID 34552061, 2021). "This study explored the role of MTDH in regulating the sensitivity of breast cancer cell lines to gemcitabine (Gem) and the potential miRNAs targeting MTDH." (PMID 34552061, 2021). "Studies in breast cancer have found that MTDH promotes breast cancer cell proliferation and tumorigenesis by activating multiple signaling pathways." (PMID 34504842, 2021). "Around the same time, AEG-1 was identified as a cell membrane protein facilitating the metastasis of breast cancer cells to the lungs and was named metadherin (MTDH)." (PMID 33918653, 2021). "To determine the functional association of MTDH with RKIP, we examined both mRNA and protein levels in human breast cancer MCF-7 cells when the MTDH gene was knocked down or overexpressed." (PMID 33802672, 2021).